SMAD6 (SMAD family member 6)
Diseases named in the same sentence as SMAD6 in open-access papers (continued):
Sharing a sentence is not in itself a finding about the gene and the disease.
glioblastoma (4 papers, 2023 to 2025). The most malignant astrocytic tumor (WHO grade IV). "Reduced LRRC4‐SAM68 interaction can downregulate circCD44 expression and subsequently affect the miR‐326/miR‐330‐5p/SMAD6 axis downstream of circCD44 in glioblastoma, influencing its progression." (PMID 40008841, 2025). "Demonstrating the role played by TGF-β-Smad1/5 signaling in this process, knockdown of the TGF-β type I receptor ALK1 or overexpression of the inhibitory Smad6 reduced endothelialisation and impaired glioblastoma progression." (PMID 39724753, 2024). "Furthermore, we establish an unprecedented therapeutic approach that is designed to inhibit endothelialisation-mediated glioblastoma progression via exogenous Smad6 expression." (PMID 39724753, 2024). "Thus, targeting Smad1/5 activity may be a novel and effective therapeutic strategy to ameliorate glioblastoma progression as demonstrated in this study via treatment with Ad-Smad6." (PMID 39724753, 2024). "In glioblastoma, tri‐partite motif‐containing protein 8 (TRIM8) and nuclear-Smad6 arbitrate the ubiquitination that persuades degradation of PIAS3, which in turn promotes STAT3 activation." (PMID 38590645, 2024). "In the case of Smad6, MH2 domain and PIAS3 ring domain are responsible for their interaction that degrades PIAS3 and promotes STAT3 activity in glioblastoma." (PMID 38590645, 2024). "In agreement with TGF-β’s described contribution to highly aggressive glioblastomas, treatment with Ad-Smad6-inhibited TGF-β signaling did not impact glioblastoma tumor size." (PMID 39724753, 2024).
bladder cancer (3 papers, 2019 to 2025). "We identified that SMAD6 plays a crucial regulatory role in the TGF-β/SMAD pathway in bladder cancer, and several biological characteristics of the C1 may be related to the deficiency of SMAD6." (PMID 38767747, 2024). "We identified SMAD6 as a key gene responsible for the differences and further explored its impact on the molecular characteristics of bladder cancer." (PMID 38767747, 2024). "Using machine learning classifiers, we identified SMAD6 as a hub gene contributing to these differences and further investigated the role of SMAD6 in bladder cancer in the single-cell transcriptome data." (PMID 38767747, 2024). "QRT-PCR yielded that the mRNA expression level of SMAD6 in bladder cancer cell lines was significantly lower than in normal bladder cells." (PMID 38767747, 2024). "Through machine learning screening, this study revealed that the TGF-β/SMAD signaling plays an important role in the progression of bladder cancer, with SMAD6 identified as a significant regulator." (PMID 38767747, 2024). "Combining the results of classification from five machine learning algorithms with survival analysis, we ultimately determined that SMAD6 can serve as a prognostic biomarker for bladder cancer." (PMID 38767747, 2024). "Finally, we performed a series of in vitro assays to verify the function of SMAD6 in bladder cancer cell lines." (PMID 38767747, 2024). "The influence of SMAD6 on bladder cancer drug sensitivity may be regulated through alterations in bladder cancer metabolism." (PMID 38767747, 2024). "Finally, we identified SMAD6 as a biomarker of bladder cancer prognosis." (PMID 38767747, 2024). "In summary, the overexpression of SMAD6 led to the downregulation of the TGF-β signaling pathway in bladder cancer, thereby inhibiting cancer cell EMT and reducing the progression and metastasis of bladder cancer." (PMID 38767747, 2024).
colorectal cancer (3 papers, 2019 to 2023). A primary or metastatic malignant neoplasm that affects the colon or rectum. "The region of gain of chromosome 1p included the colorectal cancer-associated genes REG4 and NOTCH2 and gain of 15q included the genes MAP2K1, SMAD3, SMAD6, and IGF1R, among others." (PMID 31620944, 2019). "This study found that SMAD5 and SMAD6 were significantly overexpressed in colorectal cancer." (PMID 36969909, 2023). "For example, hsa-miR-425-5p may promote tumor occurrence and metastasis by activating CTNND1 related pathway, hsa-miR-186-5p regulates TGFβ signaling pathway through expression suppression of SMAD7 and SMAD6 genes in colorectal cancer." (PMID 36561136, 2022).
glaucoma (3 papers, 2016 to 2021). Increased pressure in the eyeball due to obstruction of the outflow of aqueous humor. "•VPA reduces collagen and upregulates Smad6 in the mouse model of glaucoma filtration surgery." (PMID 26507880, 2016).
lung adenocarcinoma (3 papers, 2019 to 2021). A carcinoma that arises from the lung and is characterized by the presence of malignant glandular epithelial cells. "In one of the ILS (sample 12), one DMR of interest was hypomethylated with respect to the control tissue, and located at the gene body of SMAD6 that has been reported as a “master regulator” of lung adenocarcinoma, for which both oncogenic and tumor suppressing activities have been proposed." (PMID 34262872, 2021).
Metopic synostosis (3 papers, 2020 to 2024). Premature fusion of the metopic suture. "With the exception of some monogenic causes, including SMAD6, the aetiology of metopic synostosis is still poorly understood, owing to a likely multifactorial aetiology, involving a complex interplay of environmental and (epi)genetic factors." (PMID 38417842, 2024). "As SMAD6 variants account for 5.8% of all (non-)syndromic patients with metopic synostosis, it became, by far, the largest monogenic contributor to metopic synostosis yet identified." (PMID 36414630, 2022). "Enrichment of heterozygous missense and truncating SMAD6 variants was previously reported innonsyndromic sagittal and metopic synostosis, and interaction of SMAD6 variants with a common polymorphism nearBMP2 (rs1884302) was proposed tocontribute to inconsistent penetrance." (PMID 32499606, 2020).
non-small cell lung carcinoma (3 papers, 2010 to 2020). A group of at least three distinct histological types of lung cancer, including non-small cell squamous cell carcinoma, adenocarcinoma, and large cell carcinoma. "About prognosis, Smad6 expression was reported to be elevated in 40% of non-small cell lung cancer, and correlated to poorer outcome." (PMID 22072987, 2011). "Smad6 was recently found to contribute to patient survival in non-small cell lung cancer." (PMID 20405019, 2010).
renal fibrosis (3 papers, 2019 to 2024). A final common manifestation of a wide variety of chronic kidney diseases characterized by glomerulosclerosis and tubulointerstitial fibrosis. "The expression of genes that promote renal fibrosis (Smad2, Smad3, Smad4, Shh, Dll1) was downregulated, while the expression of genes that inhibit renal damage (Smurf1, Smurf2, Smad1, Smad5, Smad6, Smad7) was increased in the WT+miPEP31 group (PEP1/2) compared with the WT+ cPEP (SCR1/2) group." (PMID 38992718, 2024). "The TGF-β signaling pathway was also enriched in the present study, and the expressions of Smad1, Smad6, and Smad7 were significantly upregulated, which might indicate channel catfish renal fibrosis." (PMID 35747138, 2022). "This indicates that, SAA canup-regulate BMP-7 and Smad6 expressions in renal tissue, which may be one of theimportant mechanisms of anti-renal fibrosis." (PMID 30843937, 2019).
aortic aneurysm (2 papers, 2017 to 2022). A ruptured aneurysm located in the wall of the proximal portion of the descending aorta proceeding from the arch of the aorta. "Interestingly, although only a few clinical cases have been reported and the permeability is low, the mutation of I-Smad SMAD6 still leads to the formation of aortic aneurysms." (PMID 35517795, 2022).
cardiovascular malformation (2 papers, 2012 to 2013). "Recent studies have shown that TGF-β signaling is essential for the function of the cardiovascular system and in particular, SMAD6 has been reported to be associated with human congenital cardiovascular malformation." (PMID 24039762, 2013).
congenital heart disease (2 papers, 2022 to 2025). A heart disease that is present at birth. "Until now, SMAD6-deficiency has been associated with three distinctive human congenital conditions, i.e., congenital heart diseases, including left ventricular obstruction and conotruncal defects, craniosynostosis and radioulnar synostosis." (PMID 36414630, 2022).
developmental delay (2 papers, 2016 to 2020). "Considering neurodevelopmental outcomes, 11 of 15 subjects with rare damaging SMAD6 variants who are more than one year of age (and hence can have neurodevelopmental evaluation) had some form of developmental delay." (PMID 27606499, 2016).
idiopathic pulmonary fibrosis (2 papers, 2013). Idiopathic pulmonary fibrosis (IPF) is a nonneoplastic pulmonary disease that is characterized by the formation of scar tissue within the lungs in the absence of any known cause. "In contrast, genes like Gremlin-1 that may contribute to reversibility of lung fibrosis in rats, and Smad6 which in complex with Smurf-1 effectively attenuated TGF-β1 signaling, were downregulated." (PMID 24143891, 2013). "Compared to the normal lung tissue, the expressions of SMAD6 and CLIC3 are lower in tissues with idiopathic pulmonary fibrosis (GDS1252) and pulmonary adenocarcinoma (GDS1650 and GDS 3257)." (PMID 23741331, 2013). "By searching the GEO profile, we predict that SMAD6 and CLIC3 could be related to idiopathic pulmonary fibrosis and pulmonary adenocarcinomas." (PMID 23741331, 2013).
melanoma (2 papers, 2019 to 2022). A malignant, usually aggressive tumor composed of atypical, neoplastic melanocytes. "Of note, miR-186 regulates TGFβ by suppressing SMAD6-7 colorectal and inhibits cell proliferation in melanoma and in the same line, upregulation of miR-671 slows down proliferation and metastasis of A375 melanoma cells." (PMID 35163222, 2022). "Genes of special interest previously associated with various types of cancer where the SMAD6 and SOCS3 genes coupled to aggressive kidney cancer, and the MX2 gene with suggested role in melanoma pathogenesis." (PMID 30642274, 2019).
Obesity (2 papers, 2018 to 2022). Accumulation of substantial excess body fat. "Several studies indicate that aberrant expression of SMAD6, a negative regulator of TGF-α signaling, affects homeostasis of the cardiovascular system and plays a role in obesity in a mouse model." (PMID 36528638, 2022).
oral squamous cell carcinoma (2 papers, 2010 to 2020). "SMAD6 is predictive of patient survival in oral squamous cell carcinoma." (PMID 33193701, 2020).
osteoarthritis (2 papers, 2024 to 2025). A noninflammatory degenerative joint disease occurring chiefly in older persons, characterized by degeneration of the articular cartilage, hypertrophy of bone at the margins and changes in the synovial membrane. "Upregulation of miR-92a-3p exhibited pro-chondrogenic and chondroprotective effects in osteoarthritis treatment through targeting SMAD6/7." (PMID 38816719, 2024).
Osteopenia (2 papers, 2011 to 2024). Osteopenia is a term to define bone density that is not normal but also not as low as osteoporosis. "Although its in vivo functions are largely unknown, transgenic mice overexpressing Smad6 in chondrocytes showed postnatal dwarfism with osteopenia and impaired bone growth and formation, caused by delayed chondrocyte hypertrophy during endochondral ossification." (PMID 21310029, 2011).
osteoporosis (2 papers, 2011 to 2026). A condition of reduced bone mass, with decreased cortical thickness and a decrease in the number and size of the trabeculae of cancellous bone (but normal chemical composition), resulting in increased fracture incidence. "Association analysis between bone mineral density and SMAD6 SNPs in 721 Japanese postmenopausal women identified a specific SNP (rs755451), located on intron 3 of SMAD6, to be associated with lower bone mineral density in postmenopausal women, and thus increasing the risk of osteoporosis." (PMID 21310029, 2011).
prostate carcinoma (2 papers, 2020 to 2023). A carcinoma that arises from epithelial cells of the prostate gland. "For example, SMAD7 activates the TAK1-p38 MAPK pathway in human prostate cancer cells, whereas Smad6 inhibits TGF-β1-induced activation of this pathway." (PMID 37272627, 2023). "Forced expression of SMAD6 completely mitigated HNF1B‐mediated cell growth inhibition of DU145 prostate cancer cells." (PMID 33174391, 2020). "Re‐introduction of SMAD6 restored Cyclin D1 expression and cell proliferation, which supports the hypothesis that HNF1B inhibits prostate cancer cell proliferation by direct repression of SMAD6." (PMID 33174391, 2020). "All these data together demonstrated that SMAD6 is a direct target of HNF1B in the regulation of Cyclin D1 expression and cell growth of prostate cancer cells." (PMID 33174391, 2020). "The observed interaction between HNF1B with CDKN2A contributes to suppression of SMAD6 and TGF‐β signalling, which suggests that HNF1B may play important roles in prostate cancer initiation and progression." (PMID 33174391, 2020).
pulmonary arterial hypertension (2 papers, 2016 to 2025). Pulmonary arterial hypertension (PAH) is a group of diseases characterized by mean pulmonary artery pressure >20 mmHg and elevated pulmonary arterial resistance leading to right heart failure. "The aim of this study was to analyze if pathogenic SMAD6 variants also occur in patients with CHD associated with pulmonary arterial hypertension (CHD-APAH) or idiopathic PAH." (PMID 40133303, 2025). "BMP signalling is negatively autoregulated by several genes including SMAD6, Noggin and Gremlin, and autoregulators are possible targets for enhancing BMP signalling in disorders such as fibrosis and pulmonary hypertension." (PMID 27324164, 2016).
retinoblastoma (2 papers, 2020 to 2023). A malignant tumor that originates in the nuclear layer of the retina. "In retinoblastoma, the DNM3OS-miR-134-5p-SMAD6 axis can promote cell proliferation, migration, and the EMT process." (PMID 37064863, 2023).
viral infection (2 papers, 2019 to 2021). "The most down-modulated genes were related to T helper 2 pathway activation and induction of FOXP3 expression (AREG), immune tolerance (SMAD6), response to bacterial and viral infection and inflammation (CXCL8, PDE12, STX19, DFNB31), cell transport of glucose and organelles (KIF5A, SCL2A7)." (PMID 35058920, 2021). "Some anti-fibrotic factors, namely SMAD6, SMAD7, STAT1, and HGF, were also induced by the virus infection, although to a lesser extent compared to pro-fibrotic upregulation, perhaps as a counterbalance of the potent pro-fibrotic expression induced in vitro by virus infection." (PMID 31878218, 2019).
aneurysm (1 paper, 2025). Bulging or ballooning in an area of an artery secondary to arterial wall weakening. "Moreover, testing for SMAD6 variants may positively influence patient management by enabling early detection and treatment of complications such as aneurysms." (PMID 40133303, 2025).
aortic malformation (1 paper, 2012). A malformation of the aorta. "It will be interesting to test whether SMAD6 mutations are over-represented in a larger cohort of CVM patients with bicuspid aortic valves and other aortic malformations." (PMID 22275001, 2012).
aortic valve disease 2 (1 paper, 2025). Any aortic valve disease in which the cause of the disease is a mutation in the SMAD6 gene. "SMAD6 is associated with autosomal dominant (AD) Aortic valve disease 2 (MIM:614823) which features bicuspid aortic valve and aortic coarctation." (PMID 41358299, 2025).
Arrhythmia (1 paper, 2024). Any cardiac rhythm other than the normal sinus rhythm. "Eight of these associations were novel (LMNA, SMAD6, HSPB9, TMEM95, KLF1, TET2, NME3, KDM5B) and 5 genes have previously been linked to arrhythmias (SCN5A, TTN, RPL3L, PKP2, PMVK)." (PMID 38390584, 2024).
Arthritis (1 paper, 2018). Inflammation of a joint. "BMP signalling was studied to be inhibited by Smad6 its upregulation in σB treated group suggested its role in progression of arthritis." (PMID 29731966, 2018).
asthma (1 paper, 2025). "Interestingly, single nucleotide polymorphisms at or near the TGFBR1, SMAD3, and SMAD6 loci are linked to asthma risk, and at least 1 such polymorphism localizes to an open chromatin region in human MCs." (PMID 39744949, 2025).
atrial septal defect (1 paper, 2023). Interauricular communication is a congenital malformation characterized by a communication between the atrial chambers of the heart. "Such variants may prove to have causative or modifying effects on atrial septal defects in humans, as exemplified by SMAD6." (PMID 37272612, 2023).
autism (1 paper, 2016). Persistent deficits in social interaction and communication and interaction as well as a markedly restricted repertoire of activity and interest as well as repetitive patterns of behavior. "Lastly, SMAD6 is not unusually mutable, as we found no de novo SMAD6 mutations in 900 control trios comprising healthy siblings of individuals with autism." (PMID 27606499, 2016). "The odds ratios for association of all damaging variants in SMAD6 in cases vs. controls was consistent across control cohorts, ranging from 26.9 to 35.1; the odds ratios for LOFs ranged from 102.6 to infinity (owing to zero LOF’s in autism controls)." (PMID 27606499, 2016).
benign papillomas (1 paper, 2013). "When Smad7 was transduced together with HRAS, keratinocytes rapidly progressed to squamous cell carcinomas in vivo, whereas transduction with HRAS together with Smad6 or an empty vector control resulted in benign papillomas." (PMID 24047375, 2013).
calcification (1 paper, 2021). Process by which organic tissue becomes hardened by the physiologic deposit of calcium salts. "In one family, the proband’s father, who was heterozygous for the SMAD6 variant, deceased at age 80 from diffuse TAA, and had disseminated aortic calcifications, which are quite well represented in SMAD6 variant-positive individuals." (PMID 34208845, 2021).
chronic myeloid leukemia (1 paper, 2016). "The significantly enriched pathways included chemokine signaling pathway (which involved CCL2), focal adhesion (which involved THBS1 and THBS2), TGF-beta signaling pathway (which involved THBS1, THBS2, SMAD5, and SMAD6) and chronic myeloid leukemia (which involved TGFBR2 and CCND1)." (PMID 27716259, 2016).
Cognitive impairment (1 paper, 2025). Abnormal cognition is characterized by deficits in thinking, reasoning, or remembering. "Severe cognitive impairment occurred in patients with mutations in NKX6-2, PLP1, PAH gene (when untreated), and SCN2A (in early-onset type), whereas milder ID was associated with SCN2A (in late-onset type) or SMAD6 variants." (PMID 41300846, 2025).
conduction disorders (1 paper, 2024). "Rare variations in 5 genes were linked to conduction disorders (SCN5A, LMNA, SMAD6, HSPB9, TMEM95)." (PMID 38390584, 2024).
congenital Zika syndrome (1 paper, 2023). "Another study also demonstrated that Smadcin‐6, a Smad6‐derived peptide, interacts with Peli1 to disrupt Peli1‐mediated TLR4 signalling, and that it also showed therapeutic effects in lethal inflammatory disease and congenital Zika syndrome." (PMID 37341064, 2023).
COVID-19 (1 paper, 2023). A disease caused by infection with severe acute respiratory syndrome coronavirus 2. "Conversely, the BMP and TGFβ signaling pathways showed specific down-regulation in endothelial cells from COVID-19 hearts, including down-regulation of BMPR1A, BMPR1B, SMAD6, and BMP6." (PMID 37830426, 2023).
emphysema (1 paper, 2012). "The changing expression of SMAD6 and SMAD1, their localization predominantly to vascular endothelial cells, and the roles of ACVRL1 and ENG in angiogenesis support the hypothesis of aberrant tissue remodeling in the lung vasculature during emphysema pathogenesis." (PMID 22937864, 2012).